INS (insulin)
Diseases named in the same sentence as INS in open-access papers (continued):
Sharing a sentence is not in itself a finding about the gene and the disease.
diabetes (continued). "The two-hour insulin level showed non-significant decrease in our study and the insulin to glucose index and HOMA-IR had no significant change and we found two cases of impaired GTT and FBS and no case of diabetes." (PMID 24778788, 2014). "Islets from type 2 diabetic mellitus (T2DM) patients were treated with different concentrations of glucose in presence or absence of CNX-011-67 and insulin secretion was measured." (PMID 24666736, 2014). "A previous study of 168 patients with type 2 diabetes mellitus revealed that HOMA-IR and insulin were not altered by bezafibrate." (PMID 25360162, 2014). "SFT showed positive correlations with BMI (r = 0.53) and insulin (r = 0.27) and negative correlations with CIMT (r = -0.33), baPWV (r = -0.25), age (r = -0.47), and duration of diabetes (r = -0.18) in men." (PMID 24678948, 2014). "Previous studies have shown that impaired insulin secretion is the key in the conversion from normal glucose tolerance (NGT) to impaired glucose tolerance (IGT) and diabetes, and the deterioration of β-cell function does not stop after diagnosis." (PMID 24971368, 2014). "The aim of the present study was to assess the effects of insulin infusion therapy on blood gas parameters in two groups of patients, eligible for CABG, defined as A: well controlled diabetes (HbA1C < 7%) and B: non-diabetic patients." (PMID 25478539, 2014). "In type II diabetes, a non-insulin dependent DM, the body retains some endogenous insulin secretory capability; however, insulin levels are low relative to blood glucose levels and/or there is a measure of insulin resistance." (PMID 25070239, 2014). "In this study population, individuals with diabetes had higher plasma PTX3 levels than non-diabetic individuals although PTX3 did not correlate with fasting glucose, insulin or the HOMA-IR." (PMID 24705587, 2014). "Our findings indicate that tolerogenic DCs do not ameliorate diabetes in NOD mice in terms of blood glucose levels, endogenous insulin secretions, or insulitis score." (PMID 23555060, 2013). "A recent Danish study of non-diabetic adult offspring born to women with diabetes in pregnancy (type 1 diabetes and GDM) showed reduced insulin sensitivity and impaired beta cell function." (PMID 24289168, 2013). "In conclusion, UCPCR0 and UCPCR120 correlate with serum levels of insulin and C-peptide, and also with HOMA2-calculated insulin resistance in patients without diabetes." (PMID 24353253, 2013). "One of the most common drugs used for diabetes is metformin that, as discussed in the next section, accumulating evidence indicates may be protective against epithelial cancers whereas other therapeutic options such as insulin analogues may not have such an effect." (PMID 23907184, 2013). "In addition to these metabolic effects, we noted that OXT treatment tended to improve blood glucose and insulin homeostasis; under this scope, while clinical studies based on diabetic patients are needed, we employed mouse models to examine if OXT could use treat diabetes." (PMID 23700406, 2013). "Also, in non-insulin dependent diabetes mellitus pancreatic beta cells may fail to compensate for insulin resistance and the ABCA1 receptor, a cellular cholesterol transporter, plays a role as a regulator of cholesterol homeostasis and insulin secretion in these cells." (PMID 24267726, 2013). "In fact, in studies with 17 and 20 year follow-up, intensive insulin therapy achieved reduction of events in both T1DM and type 2 diabetes mellitus; patients were younger and had no manifestations of cardiovascular disease when they begun the treatment." (PMID 23398881, 2013). "Although previous studies indicated that feeding soy protein reduced SCD 1 gene expression and improved insulin sensitivity, the effect of FCE on insulin sensitivity and diabetes has not been determined." (PMID 23476706, 2013).
diabetes (continued). "Participants who were using insulin were included in the diabetes group, while those in the OHA group who did not tick the diabetes diagnosis box were assigned to diabetes uncertain group." (PMID 24245780, 2013). "In the current study, the 16 week Jiangtang Xiaozhi treatment did not lower fasting blood glucose, but it improved serum insulin and HDL cholesterol in a Western population with prediabetes or controlled diabetes." (PMID 23672597, 2013). "As high as 18% of the men with diabetes had detectable CAC, which was 3.8 fold greater than men classified as insulin sensitive without diabetes (p<0.001)." (PMID 23341938, 2013). "As expected, induction of type 1 diabetes mellitus significantly increased serum glucose level and HOMA-IR, and significantly decreased serum insulin in the untreated type 1 DM group (p<0.05) compared to non-diabetic group." (PMID 24555069, 2013). "We found a decline in the excess overall mortality rate for non-insulin-treated people with diabetes, especially with regard to CVD, compared to the people without diabetes between the periods from 1998–2002 to 2003–2007." (PMID 23837500, 2013). "Despite the benefits of intensive diabetes management, many people with T1DM and insulin-treated T2DM do not follow and/or adjust their insulin regimens as needed." (PMID 23062116, 2012). "All three measures, QUICKI, HOMA-IR and GDI, demonstrated lower insulin sensitivity among PCOS first-degree relatives versus weight, Tanner, age-matched controls without family history of PCOS, diabetes mellitus and hypertension." (PMID 22643321, 2012). "However, since we did not have information on insulin and glucose levels, or on duration of previously undiagnosed diabetes, these findings should be considered as hypothesis-generating, requiring laboratory data and information on unobserved confounders for further evaluation." (PMID 23259613, 2012). "Even though insulin resistance and diabetes do not reduce the pool of GLUT4 molecules in skeletal muscle, muscle-specific transgenic expression of GLUT4 significantly improved insulin action in diabetic mice." (PMID 27335671, 2012). "Insulin secretory defects have been observed in carriers of HNF1A-MODY and GCK-MODY with and without diabetes." (PMID 22808921, 2012). "In spite of its major role in regulating glucose utilization in insulin-sensitive tissues, genetic ablation of GLUT4 does not result in overt diabetes but instead GLUT4 null mice exhibit a range of metabolic abnormalities including marked cardiac hypertrophy." (PMID 22681646, 2012). "Despite fasting serum C‐peptide levels being an accurate and stable marker of endogenous insulin production used in patients with diabetes, it is unknown whether C‐peptide could serve as a marker of insulin resistance and predict outcomes in patients without diabetes." (PMID 23316320, 2012). "The overall study population included 206,940 patients prescribed insulin or OAD and the same number of controls without diabetes." (PMID 22164237, 2011). "Although insulin has changed the clinical course of TIDM from an acutely fatal disease to a chronic one with severe long-term complications, it does not cure diabetes." (PMID 22013504, 2011). "Type 1, insulin-dependent diabetes mellitus (IDDM), in which the body does not produce any insulin, most often occurs in children and young adults." (PMID 22134398, 2011). "One patient developed permanent insulin dependent diabetes mellitus with negative anti-GAD antibodies, and another had transient hyperglycaemia with the need of insulin-infusion for five days." (PMID 21798000, 2011). "Youth with type 1 diabetes mellitus (T1DM) are regularly subjected to periods of both low (hypoglycemia) and high (hyperglycemia) blood glucose levels, as exogenous insulin therapy does not perfectly mimic endogenous insulin needs." (PMID 20811595, 2010).
diabetes (continued). "The survey is particularly aimed at people with Type 2 diabetes, who are not treated with insulin, to try and find out how people use SMBG and the impact it has on their day-to-day diabetes management." (PMID 21092171, 2010). "Trends and significant differences remained for resistin, CRP, insulin and HOMA2-IR among a healthier subgroup of participants that was free from cancer, CVD and diabetes (data not shown)." (PMID 19788754, 2009). "Consistent with a younger age, diabetes was also less frequent amongst the SUD group 1.37% vs. 6.11% (Student's t = -2.08, df = 171.49, P = 0.0381), but the use of insulin was no different (4.11% vs. 4.58%, Student's t = -0.16, df = 270.33, P = 0.87)." (PMID 18454868, 2008). "NSSPP covered 91.5%, 87.2%, 92.2%, and 83.2% of the total cost for beneficiaries receiving insulin products only, OAA only, insulin products and OAA, and no reimbursed diabetes medications respectively." (PMID 18501012, 2008). "There were 13.2% of beneficiaries identified to be receiving insulin products, 53.5% receiving OAA, 7.4 % receiving both insulin products and OAA, and the remaining 25.9 % had no claims for diabetes medications." (PMID 18501012, 2008). "Subjects were categorized into four groups: insulin only, oral antihyperglycemic agents (OAA) only, both OAA and insulin; and no reimbursed diabetes medications." (PMID 18501012, 2008). "In this study, the average daily SMBG test strips claimed for four treatment categories was: 2 for insulin only; 1 for OAA only; 2 for insulin and OAA; and, less than 1 for no reimbursed diabetes medications." (PMID 18501012, 2008). "Of 13,564 included beneficiaries, 13.2% were categorized as insulin only, 53.5% OAA only, 7.2% both OAA and insulin, and 26.0% no reimbursed diabetes medications." (PMID 18501012, 2008). "Our data shows that our GDM women were more insulin resistant, and also had lower insulin increment at the index pregnancy compared non-GDM women especially those who subsequently developed diabetes." (PMID 17640759, 2007). "The disparities in glycemic control and insulin treatment intensity could not be explained by differences in age, body mass index, oral hypoglycemic medications, socioeconomic barriers, attitudes about diabetes care, diabetes knowledge, depression, cognitive dysfunction, or social support." (PMID 16716235, 2006). "We used Cox proportional hazards models to compare the time from diabetes diagnosis to the first prescription of each of metformin and insulin in people with and without a hospital admission record of SMI (schizophrenia, bipolar disorder or depression prior to diabetes diagnosis)." (PMID 41235789, 2026). "In patients with type 1 diabetes mellitus in the DK/DKA group, the plasma glucagon level was negatively correlated with serum CPR and serum CPR/plasma glucose ratio, suggesting relationships with decreased insulin secretion and hyperglucagonemia." (PMID 41292690, 2026). "Furthermore, dietary spermidine negatively correlates with serum glucose, insulin, HbA1C levels, and the homeostatic model assessment of insulin resistance (HOMA-IR) index in both healthy and obese individuals without diabetes." (PMID 39796620, 2025). "A key strength of this analysis is the largest cohort of individuals with diabetes using CGM in conjunction with connected insulin pens, in which we have been able to examine both the impact of isCGM engagement and insulin bolus frequency, which has not been possible with other studies." (PMID 41039947, 2025). "Furthermore, abnormal glucose metabolism and insulin secretion have been reported in GS47; however, this did not translate into a higher prevalence of overt diabetes in our cohort." (PMID 41278357, 2025). "Notably, patients prescribed GLP‐1RAs were more likely to have obesity, to be identified as White race, and to have no documented diabetes recorded in their EHR; patients prescribed long‐acting insulin were more likely to be identified as Black race." (PMID 41102137, 2025).
diabetes (continued). "In diabetes, CGM systems occasionally produce discrepancies owing to calibration errors or sensor delays, while insulin dose calculators may generate generic advice not tailored to individual patterns." (PMID 41282582, 2025). "Surprisingly, the administration of LIG was not effective in reverting any of the alterations noticed in insulin pathway protein expression; despite LIG being widely used for the therapy of diabetes, it had no efficacy in reverting signs of brain insulin resistance in our model." (PMID 40141063, 2025). "Although his diabetes workup showed negative diabetes autoantibodies (GAD, insulin, CA 152, and zinc transporter autoantibodies), he was classified as antibody-negative type 1b based on his severe presentation, personal history of autoimmune thyroid disease, and thin body habitus." (PMID 40612706, 2025). "PTP1B plays an important physiological role in the negative modulation of insulin sensitivity by dephosphorylating IRS1 and increases in PTP1B activity have been reported to be involved in the pathogenesis of insulin resistance and diabetes." (PMID 39422717, 2025). "Since the phenomenon of GV is more pronounced in patients with T1DM compared to type 2 diabetes mellitus (T2DM) patients, as individuals with T1DM do not benefit from the stabilizing effect provided by residual insulin secretion, the clinical impact of GV is emphasized in patients with T1DM." (PMID 40217883, 2025). "In both T1D and T2D as well in monogenic and other syndromic types of diabetes, the intactness of UPR is important as a molecular stress-alleviating mechanism in the production and post-modification process of the insulin molecule irrespective of the triggering factor." (PMID 41234236, 2025). "Considering the Diabetes Immunology Society criteria, all the patients were above 30 years of age at the time of diagnosis, everyone had an elevated titer of GAD antibody, and none needed insulin in the first six months of illness." (PMID 40995267, 2025). "However, as far as we know, no study has evaluated the relationship between glycaemic/insulin indices and the MSNA response to exercise in healthy individuals without diabetes." (PMID 38050866, 2024). "The Stroke Hyperglycaemia Insulin Network Effect (SHINE) randomised trial attempted to circumvent this challenge by using differing cut off glucose values for recruitment: > 6.1mmol/L for those with known diabetes, and > 8.3mmol/L for those without diabetes." (PMID 39550575, 2024). "By insulin injection (MDI vs. CSII) is the grouping variable, using the general conditions (including gender, age, BMI, disease duration, education level, employed or not, with diabetes related complications or not) as the Logistic regression analysis." (PMID 38872219, 2024). "In this study, we aim to shed more light on the role of IL6 in insulin secretion and glucose metabolism by exploring the expression patterns of IL6 and IL6R in human pancreatic islets from donors with/without diabetes and their correlation with HbA1c, BMI, age, and gender." (PMID 38667300, 2024). "Type 2 Diabetes Mellitus (T2DM) is chronic, metabolic disease that occurs when the insulin secretion by the pancreatic is defective or when the insulin-sensitive tissue is not able to respond to insulin resulting in high glycemic index." (PMID 38820419, 2024). "With lanifibranor, triglycerides, HDL-C, apolipoproteins, insulin, HOMA-IR, HbA1c, fasting glucose (FG), hs-CRP, ferritin, diastolic BP and steatosis improved significantly, independent of diabetes status: most patients with prediabetes returned to normal FG levels." (PMID 38730247, 2024). "Since the UK Prospective Diabetes Study (UKPDS), it has been known that the progressive deterioration of insulin secretion over time leads to the failure of non-insulin therapies, necessitating insulin intensification in patients with T2DM." (PMID 38559691, 2024).
diabetes (continued). "Type 1 diabetes mellitus (T1DM) is a medical disorder resulting from an autoimmune disease, wherein pancreatic β-cells are destroyed by autoreactive T cells targeting and attack, leading to insulitis and a total absence of insulin secretion." (PMID 39014283, 2024). "We have previously shown that deficiency for insulin-degrading enzyme (IDE), a ubiquitous cytosolic protease with very high affinity for insulin, induces endoplasmic reticulum (ER) stress and proliferation in islet cells and protects non-obese diabetic mice (NOD) from diabetes." (PMID 39600694, 2024). "Diabetes mellitus (DM) is a metabolic disorder characterized by disturbances in the metabolism of sugars, fats, proteins, water, and electrolytes due to an absolute or relative lack of insulin secretion and/or its utilization disorders, with hyperglycemia as its primary symptom." (PMID 38338442, 2024). "Lifestyle modifications and anti-diabetic drugs (including metformin, DPP4-inhibitors, sulfonylureas, and insulin) without any SGLT-2 inhibitors, pioglitazone or GLP-1 agonist, comprise the usual standard of care for Type 2 diabetes mellitus, which was used by three studies as control." (PMID 38267513, 2024). "For serum insulin level, the SMD was 0·25 (95 % CI (−0·04, 0·54)) in T2D patients and −0·53 (95 % CI (−1·11, 0·05)) among the participants without specified diabetes type, with only weak evidence." (PMID 35946077, 2023). "fruits on diabetes, no research has been done to directly interrogate the antidiabetic effect of PSC fruit extracts (PSC-FEs) on glucose consumption and principal mediators of the insulin signaling pathway in insulin-resistant HepG2 cells." (PMID 37158952, 2023). "Moreover, assessing insulin effectiveness and intermediate hyperglycemia, like IGT, would require other diabetes-related parameters, such as OGTT to 2hPG or HbA1c (not considered by the WHO/IDF criteria)." (PMID 37372830, 2023). "Different types of insulin used by non-DPN and DPN diabetes patients from 2016 to 2018." (PMID 37250086, 2023). "Type 1 diabetes mellitus (T1DM) occurs when the beta cells in Langerhans pancreatic islets are gradually destroyed by the immune system, leading to a decrease in the body’s insulin production capacity, eventually resulting in no insulin production." (PMID 37510181, 2023). "Diabetes mellitus (DM) is often simply referred as a group of metabolic diseases in which a person has high blood sugar as well as altered fat, carbohydrate, and protein metabolism because either the body does not produce enough insulin (Type I) or cells do not respond to the insulin (Type II)." (PMID 37143509, 2023). "In the case of diabetes, it was found that FTY720 administration led to the normalization of hyperglycemia by stimulating β-cell regeneration in vivo and regulating circulating insulin levels without affecting insulin sensitivity." (PMID 37432552, 2023). "Diabetic patients not on insulin had a higher mortality [aHR 1.32 (1.11–1.57), p = 0.0015], but similar incidence of stroke/TIA/systemic embolism, MI and major bleeding, vs those without diabetes." (PMID 35976428, 2023). "Historically called Maturity Onset Diabetes of the Young (MODY), the classic triad was diagnosis under 25 years, a family history of diabetes with autosomal dominant inheritance and minimal/no requirement for insulin." (PMID 37033247, 2023). "The overall results suggest that maternal RUPP has negative and sex-specific impacts on insulin, glucagon and ghrelin regulations in offspring and that, as young adults, male RUPP rats may be more prone to develop obesity and diabetes." (PMID 36109770, 2022). "Although we could not exactly evaluate the severity of diabetes in the study participants, we performed a subgroup analysis stratified by T2DM duration or insulin use." (PMID 35740267, 2022).